KIN (Kin17 DNA and RNA binding protein)
Description:
Involved in DNA replication and the cellular response to DNA damage. May participate in DNA replication factories and create a bridge between DNA replication and repair mediated by high molecular weight complexes. May play a role in illegitimate recombination and regulation of gene expression. May participate in mRNA processing. Binds, in vitro, to double-stranded DNA. Also shown to bind preferentially to curved DNA in vitro and in vivo (By similarity). Binds via its C-terminal domain to RNA in vitro.
Synonyms: BTCD; KIN17; Rts2
Tractability: Small molecule: a structure with a bound ligand is known. PROTAC: ubiquitination databases record sites on it; its protein half-life has been measured.
Gene: Protein-coding gene on chromosome 10 (7,750,962 to 7,787,994, reverse strand). Ensembl gene ENSG00000151657.
Subcellular location: Nucleus; Cytoplasm
Subcellular location (Human Protein Atlas): Nucleoplasm; Cytosol
Pathways (Reactome):
Metabolism of proteins: Protein methylation
Gene Ontology:
Molecular function: protein binding; RNA binding; DNA binding; double-stranded DNA binding
Biological process: DNA damage response; DNA replication; mRNA processing; mRNA splicing, via spliceosome
Cellular component: cytoplasm; cytosol; nuclear matrix; nucleoplasm; nucleus; protein-containing complex; spliceosomal complex; U2-type catalytic step 1 spliceosome
Genetic constraint (gnomAD): Loss-of-function variants: 16 observed, 31.08 expected, observed/expected ratio (o/e) 0.51, 90% interval 0.35 to 0.78. The upper end of that interval is the gene's LOEUF score, 0.78, which puts it in group 3 of 6, group 1 being the genes least tolerant of losing a copy. Missense variants: 196 observed, 246.18 expected, observed/expected ratio (o/e) 0.8, 90% interval 0.71 to 0.9. Synonymous variants: 87 observed, 87.68 expected, observed/expected ratio (o/e) 0.99, 90% interval 0.83 to 1.19.
Homologues: Orthologues: chimpanzee KIN (100% identical), macaque KIN (99% identical), guinea pig KIN (96% identical), rabbit KIN (96% identical), pig KIN (95% identical), mouse Kin (91% identical), rat Kin (91% identical), dog KIN (82% identical), tropical clawed frog kin (80% identical), zebrafish kin (74% identical), Drosophila melanogaster kin17 (50% identical), Caenorhabditis elegans dxbp-1 (46% identical).
Diseases named in the same sentence as KIN in open-access papers:
KIN is named in the same sentence as 25 diseases in open-access papers, as found by Europe PMC text mining. Sharing a sentence is not in itself a finding about the gene and the disease. The quoted sentences say what the papers report.
melanoma (2 papers, 2015 to 2021). A malignant, usually aggressive tumor composed of atypical, neoplastic melanocytes. "A study recently performed and published by our group demonstrated that KIN is differently expressed in subpopulations of melanoma from murine cell lines, according to its aggressiveness." (PMID 34449532, 2021). "KIN is overexpressed in most cancer cells studied so far, except for the cell line derived from MeWo melanoma." (PMID 34449532, 2021).
ovarian carcinoma (2 papers, 2016 to 2025). A malignant neoplasm originating from the surface ovarian epithelium. "The network based approach identified two 7-gene functional interaction modules (31: DCLRE1A, EXO1, KIAA0101, KIN, PCNA, POLD3, POLD2; 35: DKK3, FABP3, IRF1, AIM2, GBP1, GBP2, IRF2) that are associated with prognosis of ovarian cancer patients." (PMID 27806724, 2016).
cancer (8 papers, 2011 to 2025). A tumor composed of atypical neoplastic, often pleomorphic cells that invade other tissues. "To gain insight into the impact of KIN enrichment in cancer cells, we established KIN knockdown cell lines through short hairpin RNA (shRNA)." (PMID 40813768, 2025). "KIN (Kin17) protein is overexpressed in a number of cancerous cell lines, and is therefore considered a possible cancer biomarker." (PMID 34449532, 2021). "Importantly, we identified KIN as a potential target for improving the innate immune response and provided new insight into the role of activated DNA damage response proteins in cancer progression." (PMID 40813768, 2025). "Furthermore, we found that DNA-damage induced R-loops in the nucleus can activate noncanonical STING via NFκB rather than IRF3, and we highlight KIN as a potential novel target for enhancing cancer immunotherapy in ESCC." (PMID 40813768, 2025).
tumor (7 papers, 2003 to 2025). "Researchers have explored the role of KIN in the survival and metastasis of tumor cells and reported that KIN is closely related to the DDR, but the underlying mechanism has not been studied." (PMID 40813768, 2025). "To elucidate the effect of the innate immune response in vivo, we constructed an allograft tumor model in immune competent mice via KIN-knockdown mEC25 cells and control mEC25 cells." (PMID 40813768, 2025). "In contrast, the overexpression of KIN improved tumor growth and inhibited the therapeutic effects of the anti-PD-1 antibody." (PMID 40813768, 2025). "We observed a decreased tumor growth in KIN-knockdown tumors, and depletion of KIN improved the therapeutic effects of the anti-PD-1 antibody." (PMID 40813768, 2025). "Collectively, our findings identify KIN as a novel R-loop binding protein that facilitates the recruitment of the R-loop resolution complex and suppresses tumor-intrinsic innate immunity." (PMID 40813768, 2025). "To further validate our findings, we injected tumor cells subcutaneously into nude mice after they were transfected with shKIN virus or control virus in nude mice and found that depletion of KIN also inhibited tumor growth in vivo." (PMID 40813768, 2025). "We observed decreased tumor growth in KIN knockdown tumors, and this decrease was enhanced after DDP treatment." (PMID 40813768, 2025). "After treatment was ceased, mice who received KIN-8194 had undetectable or stable tumors, while mice treated with ibrutinib experienced tumor growth." (PMID 36291152, 2022). "Under hypoxic conditions, KIN-841 inhibited the proliferation of tumour cells more potently than under normoxia." (PMID 12610518, 2003). "KIN-841 showed a more potent inhibition of the proliferation against the endothelial cells than of tumour cells (P<0.05)." (PMID 12610518, 2003). "Importantly, the accumulation of R-loops resulting from KIN deficiency can activate the innate immune response in ESCC cells and improve the tumor immune microenvironment." (PMID 40813768, 2025). "Then, we applied flow cytometry to extracted tumor tissues and observed increased cytokine expression in CD8+ T cells from KIN knockdown tumors." (PMID 40813768, 2025). "We identified a key differentially expressed protein, KIN, between ESCC tumor tissues and normal tissues that may play an important role in ESCC progression." (PMID 40813768, 2025). "To investigate the role of KIN in affecting the immune system, we applied flow cytometry to assess cytokine expression in CD8+ T cells, but we did not describe the comprehensive tumor microenvironment profile." (PMID 40813768, 2025). "By comparing the proteomic differences between tumor tissues and normal tissues, we identified the key DDR protein KIN in ESCC, which has not been adequately studied." (PMID 40813768, 2025).
infection (2 papers, 2014 to 2026). The state of being infected such as from the introduction of a foreign agent such as serum, vaccine, antigenic substance or organism. "With the PCR assays, considering the dogs were infected when positive signals were observed before or after hybridization, the infection rates reached 87.5% (35/40), 97.5% (39/40) and 82.5% (33/40) for RIB, INF and KIN PCRs, respectively while with the gp63PCR it was 42.5% (17/40)." (PMID 25153833, 2014). "R-genes belonging to the classes of KIN (kinase domain), RLP (receptor-like protein), and RLK (receptor-like kinase) were significantly expressed while TFs, bHLH (basic helix-loop-helix), and GeBP (glabrous-enhancer-binding protein) were downregulated with prolonged infection." (PMID 41705620, 2026).
KIN also shares sentences with these, for which no sentence is quoted: breast carcinoma (6 papers); cervical cancer (4); hepatocellular carcinoma (2); benign tumors (1); Brain atrophy (1); breast adenocarcinoma (1); breast tumors (1); cervical adenocarcinoma (1); chromosomal instability syndromes (1); colorectal cancer (1); esophageal cancer (1); esophageal squamous cell carcinoma (1); lymph node metastasis (1); metastatic melanoma (1); non-small cell lung carcinoma (1); osteosarcoma (1); ovarian serous adenocarcinoma (1); Rubinstein Taybi 2 syndrome (1); squamous carcinoma (1); sunburn (1).